JAK2 (Janus kinase 2)
Diseases named in the same sentence as JAK2 in open-access papers (continued):
Sharing a sentence is not in itself a finding about the gene and the disease.
myelofibrosis (continued). "Univariate logistic regression analysis showed that age, gender, interval from first diagnosis to the treatment, myelofibrosis, splenomegaly, JAK2 mutation burden, risk stratification, history of HU treatment, and history of thrombosis did not affect CHR." (PMID 34993148, 2021). "Pacritinib is a novel “multi-target” agent, developed for myelofibrosis, which inhibits JAK2/FLT3/IL-1 receptor associated kinase (IRAK1)/colony stimulating factor 1 receptor (CFS1R)." (PMID 35056105, 2021). "A total of 2,734 cells were examined—678 healthy donor cells plus 2,056 myelofibrosis cells (388 JAK2 wild type and 1,668 JAK2V617F mutated)." (PMID 32386542, 2020). "The majority of cases of polycythemia vera, essential thrombocytopenia, and myelofibrosis are characterized by an activating valine to phenylalanine mutation in JAK2 (JAK2 V617F) that drives the development of these neoplasms." (PMID 33521321, 2020). "The discovery of JAK2 mutations allowed the development of JAK2 inhibitors for target therapies, including ruxolitinib, approved for patients with primary or secondary myelofibrosis and hydroxyurea‐resistant or intolerant PV patients." (PMID 31033209, 2019). "JAK-STAT signaling dysregulation has been noted in inflammatory disorders, and aberrant JAK2 pathway activation has been implicated in myelofibrosis and polycythemia vera." (PMID 31560729, 2019). "Ruxolitinib is a JAK1/2 inhibitor that is approved for the treatment of myelofibrosis and polycythemia vera in JAK2 gain of function mutations." (PMID 31636267, 2019). "Ruxolitinib (ruxo) is a potent JAK1/2 inhibitor used for the treatment of high-risk myelofibrosis and Fedratinib (fed) is a JAK2 specific inhibitor currently in Phase III trials for high-risk myelofibrosis." (PMID 31817106, 2019). "To explore this option in UBC, we used RX, a potent JAK1/JAK2 inhibitor approved for the treatment of intermediate/high risk myelofibrosis." (PMID 31438567, 2019). "Ruxolitinib is an oral selective Janus-associated kinase 1 (JAK1) and JAK2 inhibitor that was initially approved by the FDA in 2014 for treatment of myelofibrosis." (PMID 30519495, 2018). "NCB1824, a small-molecule inhibitor of both JAK1 and JAK2, suppresses levels of phosphorylated STAT3 in subjects with wild-type JAK2 or with the gain-of-function V617F JAK2 mutation, as revealed in a phase 1–2 clinical trial of myelofibrosis patients." (PMID 30217007, 2018). "Patients with the myelofibrosis (MF) carrying activating mutant allele of JAK2 exhibited rapid, significant reduction in disease burden and durable clinical benefit in patients following ruxolitinib." (PMID 29515770, 2018). "A study conducted on 103 MPN patients in Korea revealed that JAK2 V617F mutation was correlated with older age, higher neutrophil count, greater rates of organomegaly, thrombotic events and myelofibrosis in ET patients." (PMID 30564475, 2018). "The randomized, double-blind, placebo-controlled, phase 3 COMFORT-I trial evaluated the JAK1/JAK2 inhibitor ruxolitinib in patients with intermediate-2/high-risk myelofibrosis." (PMID 28228106, 2017). "In adults with myelofibrosis, which is commonly associated with the JAK2-V617F mutant, symptoms were relieved by the JAK inhibitor ruxolitinib." (PMID 28185911, 2017). "Myelofibrosis (MF) is a clonal neoplasia of the hemopoietic stem/progenitor cells associated with genetic mutations in the Janus kinase 2 (JAK2), myeloproliferative leukemia virus oncogene (MPL), and calreticulin (CALR) genes." (PMID 27672242, 2016). "Ruxolitinib, a potent inhibitor of Janus kinase (JAK) 1 and JAK2, was associated with an overall survival benefit and improvements in splenomegaly and patient-reported outcomes in patients with myelofibrosis in the two phase 3 COMFORT studies." (PMID 26380150, 2015). "Ruxolitinib, a JAK1 and JAK2 inhibitor drug, has recently been approved for the treatment of patients with high- or intermediate-risk myelofibrosis with symptomatic splenomegaly." (PMID 26316485, 2015).
myelofibrosis (continued). "About half of patients with myelofibrosis carry a gain-of-function mutation in the Janus kinase 2 gene (JAK2 V617F) that contributes to the pathophysiology of the disease." (PMID 26316489, 2015). "One patient with Janus kinase 2 (JAK2)-mutated myelofibrosis transformed to AML remains on treatment beyond 31 cycles (manuscript in preparation)." (PMID 26113989, 2015). "Ruxolitinib, a JAK1 and JAK2 inhibitor drug, has recently been approved for the treatment of patients with high- or intermediate-risk myelofibrosis (MF) with symptomatic splenomegaly." (PMID 26316485, 2015). "In November 2011, the US Food and Drug Administration approved the use of the JAK1- and JAK2-selective inhibitor ruxolitinib for the treatment of patients with intermediate- or high-risk myelofibrosis." (PMID 26316489, 2015). "The result that homozygosity for JAK2V617F is a risk factor for BT in PMF parallels the finding that accumulation of JAK2 mutated alleles contributes to transformation into myelofibrosis of patients with polycythemia vera." (PMID 23555782, 2013). "The presence of the JAK-2 mutation suggests polycythemia vera, essential thrombocytosis, or myelofibrosis, while a positive BCR-ABL mutation is diagnostic for chronic myeloid leukemia." (PMID 23936692, 2013). "The somatic V617F gain-of- function mutation in exon 14 of JAK2 gene, and less commonly exon 12 mutation of JAK2 have found in greater than 95% of patients with polycythemia vera and about 50% of patients with essential thrombocythemia and myelofibrosis ‐." (PMID 22549126, 2012). "In November 2011, the US Food and Drug Administration approved the use of the JAK1- and JAK2-selective inhibitor ruxolitinib for the treatment of patients with intermediate or high-risk myelofibrosis, including PMF, post-PV MF, and post-ET MF." (PMID 22852872, 2012). "Myelofibrosis (MF) in 50% of cases is driven by an activating JAK2 mutation, mostly V617F." (PMID 40269271, 2025). "Furthermore, there are publications showing that a higher VAF of JAK2 mutation (> 50%) is associated with increased transformation to myelofibrosis as a sign of higher disease activity." (PMID 40906032, 2025). "Additionally, a case has been reported with primary myelofibrosis and triple mutations in JAK2, CALR, and MPL." (PMID 41439212, 2025). "However, patients with JAK2 V617F and JAK2 exon 12 mutations have a similar risk of thrombosis, progression to myelofibrosis or leukemia, and mortality." (PMID 40507313, 2025). "Notably, strategies that block pathogenic cytokines via inhibition of the JAK2/STAT3 pathway have emerged as essential treatments for clinical conditions such as myelofibrosis." (PMID 39919369, 2025). "However, these patients are at a higher risk of progression to myelofibrosis than those with the JAK-2 mutation, especially if they are resistant or intolerant to Hu therapy." (PMID 41464542, 2025). "Moreover, JAK2 V617F allele burden >50% is associated with an adverse MPN-SVT hematologic outcome (incidence of myelofibrosis, blast phase MPN or death)." (PMID 38338802, 2024). "In fact, the prevention of thrombopoietin expression in a transgenic mouse model of PV eliminated the PV phenotype, including splenomegaly, myelofibrosis, osteosclerosis, erythrocytosis, leukocytosis, and thrombocytosis, even though the JAK2 V617F mutation was still expressed." (PMID 39598101, 2024). "In 2005, it was found that myelofibrosis was associated with the V617 mutation locus of JAK2." (PMID 36671504, 2023). "The majority of JAK2 mutations identified in myelofibrosis are V617F." (PMID 37760623, 2023). "On the basis of extensive clinical data on myelofibrosis, a disease type that frequently harbors the JAK2 V617F mutation, JAK2-activating mutations may predict sensitivity to JAK2 inhibitors such as ruxolitinib." (PMID 36551764, 2022).
myelofibrosis (continued). "An early, hypercellular primary myelofibrosis with monocytosis was excluded; however, because these are associated with high allelic burden of JAK2^V617F, higher proportion of MF-2/MF-3 reticulin fibrosis, and clustered megakaryocytes with a high degree of histologic atypia." (PMID 35228982, 2022). "Moreover, it has been shown that JAK2 mutation induces the accumulation of ROS in the hematopoietic stem cell compartment of knock-in (KI) mouse model and in myelofibrosis patients, suggesting the importance of oxidative stress in MF pathogenesis." (PMID 35052617, 2022). "More extensive use of the JAK1/JAK2 inhibitor ruxolitinib is associated with a greater risk of mycobacterial infections (Mycobacterium tuberculosis and atypical mycobacterial infections) in the treatment of patients with myelofibrosis and polycythemia vera." (PMID 36159783, 2022). "Myelofibrosis is a disease, which is often positive for a JAK2 V617F mutation." (PMID 36354687, 2022). "Patients with myelofibrosis may have one of three driver mutations (JAK2, CALR and MPL), or lack all three (triple negative patients)." (PMID 34017327, 2021). "Calreticulin (CALR) mutation type 1 frequencies in ET are estimated between 7% and 11% and ET patients carrying CALR type 1 mutation are associated with lower risk of thrombosis but higher risk of myelofibrosis transformation compared to ET patients with JAK2 mutation." (PMID 34040959, 2021). "After being diagnosed with myelofibrosis, our patient exhibited several risk factors of leukemia, such as high white blood cell counts, high platelet counts, being >50 years’ old, and carrying a JAK2 mutation." (PMID 31852097, 2019). "Myelofibrosis and JAK2 V627 mutation were discovered during restaging of the patient." (PMID 31781224, 2019). "Moreover, loss of Ezh2 accelerates the development of myelofibrosis and decreases survival in Jak2-V617F–driven MPN and Runx1 mutated MDS, identifying EZH2 as a tumor suppressor." (PMID 30890554, 2019). "Ruxolitinib, an oral JAK1 and JAK2 inhibitor, is approved in the US for patients with intermediate or high-risk myelofibrosis (MF), a chronic neoplasm associated with aberrant myeloproliferation, progressive bone marrow fibrosis, splenomegaly, and burdensome symptoms." (PMID 24283870, 2013). "A low clonal burden of JAK2 V617F is typically associated with phenotypes such as clonal hematopoiesis of indeterminate potential or essential thrombocythemia (ET), while a high clonal burden is more often linked to polycythemia vera (PV) or post-PV myelofibrosis (MF)." (PMID 41226376, 2025). "Myelofibrosis (MF) is a hematological condition characterized by uncontrolled bone marrow proliferation often attributed to acquired driver mutation-mediated constitutive activation of the Janus kinase 2 (JAK2)-signal transducer and the activator of the transcription signaling pathway." (PMID 40276423, 2025). "Therefore, the decreased JAK2 V617F allele burden following ropeginterferon alfa-2b treatment may have contributed to a reduced myelofibrosis transformation risk." (PMID 38951434, 2024). "Indeed, this group of diseases, which include polycythemia vera (PV), essential thrombocythemia (ET), and myelofibrosis (MF), is characterized by the uncontrolled clonal expansion of multipotent bone marrow progenitors driven by acquired mutations in the JAK2, CALR, and MPL genes." (PMID 38338802, 2024). "In addition, some cases of MDS with fibrosis have been associated with a JAK2 V617F mutation suggesting that this may be responsible for myelofibrosis in a subset of MDS cases, postulating a possible myeloproliferative biology background." (PMID 36810551, 2023). "Compared to JAK2 V617F-positive PV patients, those with exon 12 mutations had significantly higher hemoglobin levels, reduced serum erythropoietin levels, and lower platelet and leukocyte counts at diagnosis, but a similar incidence of thrombosis, myelofibrosis, leukemia, and death." (PMID 35456443, 2022).
myelofibrosis (continued). "In PV patients, although the role of JAK2 V617F mutation in progression toward fibrosis is currently unknown, transition from heterozygoty to homozygoty for JAK2 may represent an important step in the progression toward post-PV myelofibrosis." (PMID 17210076, 2007). "We report the case of a 54-year-old woman with Janus kinase 2 (JAK2)-positive primary myelofibrosis and long-standing transfusion-dependent cytopenias who presented with multiple firm, erythematous-to-violaceous nodular lesions on the trunk." (PMID 41873295, 2026). "The newest JAK1/JAK2 inhibitor, momelotinib (CYT387), has been studied for the treatment of intermediate- to high-risk primary and secondary myelofibrosis (MF)." (PMID 40699626, 2025). "Ruxolitinib was the first JAK2 inhibitor approved for the treatment of primary and secondary myelofibrosis." (PMID 40123795, 2025). "Fedratinib is best known for its ability to inhibit JAK2 and is an oral medication used in the treatment of myelofibrosis." (PMID 40362543, 2025). "Among myelofibrosis patients with symptomatic anemia, momelotinib stands out as the only JAK2 inhibitor that increases erythropoiesis by inhibiting ACVR1-mediated hepcidin expression." (PMID 40507313, 2025). "In this study, we systematically investigated the antitumor potential of fedratinib, a JAK2 inhibitor approved for myelofibrosis, against esophageal squamous cell carcinoma (ESCC) using integrated in vitro, in vivo, and patient-derived organoid (PDO) models." (PMID 41476794, 2025). "The far more JAK2-selective inhibitor fedratinib is now approved for the treatment of myelofibrosis and has demonstrated significant activity in a cohort of patients who had lost response to ruxolitinib treatment." (PMID 40140631, 2025). "In liver fibrosis, HSPB1 activates JAK2/STAT3 and TGF-β1/Smad pathways, while it regulates cell proliferation and directly interacts with JAK2/STAT5 in myelofibrosis." (PMID 39863585, 2025). "The recently approved luspatercept, which targets the bone morphogenetic protein-SMAD signaling pathway, and momelotinib, a newer JAK1/JAK2 inhibitor with anemia-related efficacy, have shown benefits in managing anemia in myelofibrosis." (PMID 40507313, 2025). "A recent study demonstrated, that SRSF2 mutations can impair JAK2-V617F signaling by missplicing of JAK2 leading to reduced TGF-β levels and attenuation of myelofibrosis." (PMID 40140631, 2025). "In mice with JAK2 p.V617F-driven PV, Osm knockout reduced the expression of markers of T-cell exhaustion and disease progression, including polycythemia and myelofibrosis." (PMID 41372120, 2025). "A 59-year-old man with Janus kinase-2 (JAK2) V617F mutation-positive polycythemia vera, evolving to myelofibrosis presented with a right thigh hematoma." (PMID 40636934, 2025). "Current therapeutic guidelines for post-ET myelofibrosis patients comprise initiation of a JAK-2 inhibitor (e.g., ruxolitinib) and consideration of stem cell transplant as definitive treatment." (PMID 41464542, 2025). "Fedratinib is a selective JAK2 inhibitor approved for the treatment of myelofibrosis, where it functions by disrupting the JAK–STAT signaling pathway, a critical regulator of hematopoietic cell proliferation and survival." (PMID 41325773, 2025). "Ruxolitinib, a selective JAK1 and JAK2 inhibitor, is frequently used to treat polycythemia vera (PV), myelofibrosis, and graft-vs.-host disease (GVHD)." (PMID 41164159, 2025). "Several JAK2 inhibitors, including ruxolitinib, fedratinib, and momelotinib showed remarkable clinical activity in primary and secondary myelofibrosis (MF) patients." (PMID 40269271, 2025). "To identify cytokines that are altered in the JAK2V617F transgenic myelofibrosis mouse model, we measured the serum levels of 32 cytokines using the Mouse 32-Plex Cytokine Array in JAK2 WT and JAK2V617F mice." (PMID 40386398, 2025). "JAK2 p.V617F-induced PV as well as subsequent myelofibrosis can be successfully reversed by OSM inhibition." (PMID 41372120, 2025).
myelofibrosis (continued). "This case demonstrates the critical role of JAK1 and JAK2 gene transcription in antifungal defense, particularly in patients receiving ruxolitinib therapy, a JAK1 and JAK2 inhibitor, for PV or myelofibrosis." (PMID 41164159, 2025). "The JAK2 inhibitor fedratinib is an FDA‐approved drug with an indication for myelofibrosis, and the MEK inhibitor trametinib is clinically used to treat various cancers, including malignant melanoma and nonsmall cell lung cancer." (PMID 39400496, 2025). "In JAK2 V617Fpos MPN, the frequency of additional somatic mutations is related to the MPN subtype, with incidence rates highest in myelofibrosis." (PMID 40681596, 2025). "In patients with PCM1:JAK2, the bone marrow is typically hypercellular demonstrating eosinophilia, erythroid hyperplasia with dyserythropoiesis, and myelofibrosis." (PMID 38611061, 2024). "Drugs targeting JAK2 are considered for the treatment of immunological diseases such as UC, rheumatoid arthritis, and myelofibrosis." (PMID 38707907, 2024). "The ongoing phase 3 INDEPENDENCE trial of luspatercept in combination with a JAK2 inhibitor will shed additional light on this approach to anemia management in transfusion-dependent patients with myelofibrosis." (PMID 39682250, 2024). "Long-term treatment with JAK2 inhibitors such as fedratinib or ruxolitinib has been observed to lower JAK2 V617F VAFs in myelofibrosis (MF) patients, correlating with clinical improvements like reduced spleen size and decreased recurrence post-transplant." (PMID 38730632, 2024). "Following a diagnosis of myelofibrosis and treatment with JAK2 inhibitors, his ILD improved significantly." (PMID 39659792, 2024). "We concluded that when JAK2 inhibitors are used to treat myelofibrosis, they also inhibit IL-6-induced JAK2-related signal transduction in the lungs to achieve therapeutic effects." (PMID 39659792, 2024). "In respect of JAK2 kinase inhibitors, these have already been deployed as treatment of human disease (e.g. polycythaemia vera, myelofibrosis) and for veterinary medicine in companion animals." (PMID 39817173, 2024). "JAK2 V617 mutation in the background of EZH2 knockout mice resulted in a shift in differentiation toward megakaryopoiesis and development of myelofibrosis at the expense of erythropoiesis." (PMID 38339265, 2024). "However, we speculate that this finding could be attributable to myelofibrosis subtypes, as MF patients with high JAK2 V617F allele burden display increased basophile counts and also improved survival, which might indicate patients with post-PV myelofibrosis that evolved from an undiagnosed PV." (PMID 38611094, 2024). "Most patients with myelofibrosis (MF) discontinue ruxolitinib (JAK1/JAK2 inhibitor) in the first 5 years of therapy due to therapy failure." (PMID 37894394, 2023). "Considering the crucial role of JAK2 in the pathogenesis of myeloproliferative illness, JAK2 inhibitors, ruxolitinib, and fedratinib were approved as new treatments for myelofibrosis and polycythemia vera." (PMID 36671504, 2023). "We therefore assessed the activity of CBL0137 in primary patient samples and murine models of Jak2-mutated MPN and found it preferentially targets CD34+ stem and progenitor cells from myelofibrosis patients by comparison with healthy control cells." (PMID 37253035, 2023). "Currently, ruxolitinib, fedratinib and pacritinib are three FDA-approved JAK2 inhibitors (JAKi) for treatment of myelofibrosis (MF)." (PMID 36599841, 2023). "There are some JAK1 inhibitors used in clinics, such as Ruxolitinib, a selective inhibitor of JAK1 and JAK2, for the treatment of myelofibrosis and polycythemia." (PMID 37895906, 2023).